APOD (apolipoprotein D)
Diseases named in the same sentence as APOD in open-access papers (continued):
Sharing a sentence is not in itself a finding about the gene and the disease.
tumor (continued). "Upon apoD becoming abundantly present in stromal cells, the senescence of these stromal cells is not a good sign due to the decrease in something that could otherwise restrain the invasion of tumor cells, such as tissue inhibitors of metalloproteinases and serine." (PMID 32306242, 2020). "Additionally, APOD+ myCAFs showed significant interactions with cytotoxic T and NK cells through the CXCL13 and CXCL16 signaling pathways, potentially contributing to tumor regression." (PMID 40107247, 2025). "Likewise, our data showed HER2low TNBC actively participated in activities with regard to tumor metabolism and growth pathways with MUCL1, PTN, SCGB2A2 and APOD highly expressed, revealing an increased metabolic and proliferative capacity contained." (PMID 36998014, 2023). "In total, five populations were designated tumour clusters, which had various features: (TumourC0) CD74 and APOD; (TumourC1) IF16, JUN and HSPA1A; (TumourC2) S100B and SCRG1; (TumourC3) NEAT1 and MALAT1; and (TumourC4) WFDC2 and RNASE1 (HLA‐DRA, CD68, CD3D, CD3E)." (PMID 37784253, 2023). "The protein expression of PCOLCE2, APOD and TIMP1 displayed no significant changes in tumor and normal thyroid tissues." (PMID 36387901, 2022).
cancer (43 papers, 2009 to 2026). A tumor composed of atypical neoplastic, often pleomorphic cells that invade other tissues. "APOD is known to modulate important processes such as inflammation and antioxidation, and its expression is closely associated with numerous malignant tumors." (PMID 40989158, 2025). "The biological functions of ApoD are known to be associated with neuroprotection, metabolic processes, and cancer, partly owing to its anti-oxidative stress and anti-inflammatory properties." (PMID 38375199, 2024). "For fibroblasts, we recognized five subgroups, including APOE+ cancer-associated fibroblasts (CAFs), APOD+ CAFs, myofibroblastic CAFs (myoCAFs), inflammatory CAFs (iCAFs), and proliferating cells." (PMID 37475874, 2023). "In contrast, the SLC22A17 and APOD genes were negatively associated with RNAss and DNAss in most cancers." (PMID 34306002, 2021). "However, enhanced expression of APOD was associated with increased drug resistance to Varbulin, Rigosertib, and RX-5902 in cancer cells." (PMID 36467500, 2022). "Hence, we detected the expression of SLC22A17 and APOD in 33 types of cancers and determined the association of the two genes with cancer stemness-related indicators." (PMID 34306002, 2021). "Notably, significant post-treatment upregulation of SELP+ high endothelial venules (HEVs) and APOD+ myofibroblastic cancer-associated fibroblasts (myCAFs), alongside a decline in STMN1+ capillary endothelial cells (cECs), is specific to the immunochemotherapy cohort." (PMID 40107247, 2025). "Survival analyses across multiple cancer types confirmed the prognostic relevance of resistance-associated genes, including SPINK1, PHGR1, and APOD." (PMID 41724379, 2026). "We identified a progenitor cell population highly enriched in samples from invasive and chemo-resistant carcinomas, characterized by a well-defined multigene signature including APOD, DCN, and LUM." (PMID 38466528, 2024). "The opposite effect was observed in apolipoprotein D (Apo-D) concentration, which was lower in childhood cancer survivors than in the control group (3.66 ± 0.57 vs. 17.88 ± 11.71 mg/dL; p < 0.05)." (PMID 36142534, 2022). "Experimental research on ApoD has been accumulating, encouraged by numerous findings of ApoD relationship to many human diseases, from cancer to cardiovascular, metabolic or neurodegenerative conditions." (PMID 34690812, 2021). "We observed that APOD was dysregulated in 17 types of cancers and that SLC22A17 was dysregulated in 16 types of cancers, with significant p-values." (PMID 34306002, 2021). "In the proliferative process of prostate cancer cells, stimulating the secretion of apoD contributes to the inhibition of cancer cell proliferation." (PMID 32306242, 2020). "The APOD is also classified and categorized as exosomal protein from cancer cells under the KEGG database." (PMID 30813444, 2019). "Seven of these predicted proteins (NCAM1, CNTN1, SCG2, CADM1, IL-8, NPTX1, and APOD) were identified in five databases (SignalP 4.1, SecretomeP 2.0, Vesiclepedia, Human Cancer Secretome, and Plasma Proteome), giving support to their relevance in NSCLC." (PMID 31455042, 2019). "Many previous reports demonstrated the function of APOD in various physiological and pathological states, including oxidative stress responses, lipid metabolism, molecular regulation in cancer, and aging." (PMID 30813444, 2019). "In vitro cell experiments showed that the mRNA and protein levels of APOD, GPC3, and SERPINE1 were upregulated in the STAD cell line and that APOD knockout significantly reduced cancer cell proliferation, migration, and invasion levels and increased the apoptotic capacity of the STAD cell line." (PMID 41438490, 2025). "Given that interactions between nervous system and cancer cells can promote cancer progression, we hypothesized that patients with co-high expression of notable interactions (APOD_VDAC1, APOD_PDZK1IP1, and CLDN4_APOD) would have poor prognosis." (PMID 40052442, 2025).
cancer (continued). "ApoD gene expression is affected in several pathologies, such as HDL (high-density lipoprotein) familial deficiency and many others including central nervous system disorders and cancer." (PMID 39062058, 2024). "APOD, ACTA2, PDK4 and SAPCD2 have all been linked to the development of cancer in several studies." (PMID 38436027, 2024). "According to a recent study, a reduction in APOD levels was linked to the initial stages of cancer development, specifically stages I and II, but not to later stages." (PMID 38067270, 2023). "The results showed that high expression of TSLP, RASGRP1, APOD, and PTGER3 was correlated with cancer cell drug sensitivity to a variety of chemotherapeutic drugs, especially APOD, which was highly correlated with drug sensitivity to ARQ-680, SB-590885, PLX-4720, vemurafenib, and others." (PMID 36467500, 2022). "SLC22A17 and APOD were found to be dysregulated in diverse cancers." (PMID 34306002, 2021). "A prognostic model constructed with SLC22A17 and APOD might have vital roles across multiple types of cancers." (PMID 34306002, 2021). "ApoD in cancer cells may inhibit cell proliferation and be beneficial to patient prognosis, while apoD in stromal cells has the opposite effect on cancer cells and may be unfavorable to patient prognosis." (PMID 32306242, 2020). "While the roles of specific APOs like APOC2, APOD, and APOM are still under investigation, continued research promises to deepen our understanding of how the APO family interacts with cancer." (PMID 38067270, 2023). "In almost all cancers, SLC22A17 and APOD have positive relationships with the StromalScore, ImmuneScore and ESTIMATEScore." (PMID 34306002, 2021). "Both TAP1 and APOD are closely related to antitumor immunity, and studies have shown that TAP1 plays an important role in a variety of cancers." (PMID 34247148, 2021). "In the current paper, we conclude that apoD mediates binding of HDL to LDL and to growing T24 carcinomas, thereby highlighting the importance of apoD in lipid metabolism." (PMID 25513803, 2014). "When comparing RM with PC, we identified key regeneration-related genes APOD and IBSP, along with several significant pathways: cAMP signaling pathway (HHIP), cytokine-cytokine receptor interaction (IL17D), pathways in cancer (HHIP, DAPK2), and biosynthesis of cofactors (RDH12, HAAO)." (PMID 39684926, 2024). "Then, we analyzed the expression levels of APOD and SLC22A17 in 33 types of cancers." (PMID 34306002, 2021). "Not surprisingly, we found that APOD and SLC22A17 have a wide range of stromal scores in association with 33 different cancer types." (PMID 34306002, 2021). "Interestingly, we observed that the APOD and SLC22A17 genes were negatively correlated with RNAss and DNAss in almost all of the cancer types." (PMID 34306002, 2021). "Thus, the high expression of apoD, low expression of ER, and weak activity of MAPK all contribute to the low proliferation of cancer cells, which indicates a better prognosis for BC patients." (PMID 32306242, 2020). "It has been suggested that APOD, which has a specific protein profile for FTC and PTC, may modify the proliferative activity of cancer cells." (PMID 19893615, 2009). "Interestingly, five KEGG pathways are predicted as APOD interactome, including NOTCH signaling pathway (04330), thyroid signaling pathway (04919), PPAR signaling pathway (03320), fat digestion and absorption (04975), and transcriptional misregulation in cancer (05202)." (PMID 30813444, 2019).
neurodegenerative disease (20 papers, 2013 to 2025). A disorder of the central nervous system characterized by gradual and progressive loss of neural tissue and neurologic function. "In this sense, the 5’ UTR variation discovered in mouse ApoD should be further explored in the human gene, given its potential role in regulating ApoD response to aging and many neurodegenerative diseases, both causally related to oxidative stress." (PMID 32559215, 2020). "Elevation in APOD expression has been associated with a number of pathological conditions including neurodegenerative disease." (PMID 33260536, 2020). "ApoD may be a specific, sensitive, easily obtained, cost-effective biomarker for neurodegenerative diseases and its applications in diagnostic practices, treatment strategies, and advancing neurodegenerative disorders’ management." (PMID 39767175, 2024). "CLU like ApoD, has been implicated in ameliorating oxidative stress in neurodegenerative diseases and may be involved in the death of damaged neurons (Törnqvist, Liu, Aldskogius, Holst, & Svensson, 1996)." (PMID 30585359, 2019). "ApoD has recently been the subject of research on neurodegenerative diseases and cardiovascular function." (PMID 38339027, 2024). "Because it is overexpressed during many neurodegenerative diseases and stresses, ApoD is considered an important factor in brain protection and repair." (PMID 33923459, 2021). "The capability of EVs to cross the blood-brain barrier (Krämer-Albers, 2017) opens up new research avenues to explore the use of systemically administered ApoD-positive exosomes to treat neurodegenerative diseases." (PMID 30687015, 2018). "Apolipoprotein D (ApoD), a lipocalin transporter of small hydrophobic molecules, plays an important role in several neurodegenerative diseases." (PMID 29780571, 2018). "Apolipoprotein D (Apo D), a glia-derived lipocalin, has emerged in recent decades as a neuroprotective molecule involved in lipid transport, oxidative stress regulation, and inflammation control during aging and neurodegenerative diseases like MS." (PMID 40943611, 2025). "That suggests that the systemic administration of ApoD in the form of exosomes could be a potential treatment for neurodegenerative diseases." (PMID 39767175, 2024). "Furthermore, since oxidative stress is a major source of progression of AD and ApoD acts in an antioxidant manner and is upregulated in this neurodegenerative disease, studies on the behavior of ApoD in this specific region of the brain are of interest." (PMID 37237893, 2023). "These discoveries help us reframe our understanding of the neuroprotective role of this lipid binding protein and open up new research avenues to explore the use of systemically administered ApoD-loaded exosomes that can cross the blood-brain barrier to treat neurodegenerative diseases." (PMID 30687015, 2018). "We have previously shown that transgenic mice (Tg) overexpressing human apoD (H-apoD) in the brain are protected against neurodegeneration and injuries suggesting that apoD could be a good therapeutic target against neurodegenerative diseases." (PMID 26083030, 2015). "Thus, ApoD in the tear warrants further study in PD patients and those with other neurodegenerative diseases to assess whether it has a true neuroprotective effect in such patients." (PMID 35076620, 2022). "APOD is generally overexpressed in neurodegenerative diseases, whereas in PEX syndrome, an age-related disease of the extracellular matrix, a significant underrepresentation of APOD in the AH could be detected." (PMID 34943212, 2021). "Unfortunately, no data exist on ApoD concentration in the urine and peripheral tissues from Alzheimer and other neurodegenerative diseases patients." (PMID 33923459, 2021).
neurological diseases (13 papers, 2008 to 2024). "On the other hand, apoD encodes a lipocalin, which has been described in higher vertebrates as a protector of neurological disorders, controlling peroxidated lipids and regulating inflammatory processes involved in neuronal damage." (PMID 34832544, 2021). "Moreover, ApoD is up-regulated in several human neurological disorders, such as Alzheimer’s disease (AD), Schizophrenia, Parkinson’s disease, and multiple sclerosis, and serves as an early diagnostic marker for a variety of cancers and neurological diseases." (PMID 33490085, 2020). "The localized solution phase information obtained from HDX-MS can help make ApoD an important therapeutic target for several devastating neurological diseases." (PMID 32709043, 2020). "ApoD is known to bind AA with high affinity, and nervous system disorders with altered AA levels concur with ApoD over-expression." (PMID 25426024, 2014). "The lipocalin apolipoprotein D (Apo D) is upregulated in peripheral nerves following injury and in regions of the central nervous system, such as the cerebral cortex, hippocampus, and cerebellum, during aging and progression of certain neurological diseases." (PMID 24167586, 2013). "Thus, changes in APOD and APOM levels could contribute to the association of the PON1 genotype with cardiovascular and neurological diseases." (PMID 33260536, 2020). "ApoD is one of the few genes consistently over-expressed in the aging brain of all vertebrate species, and no nervous system disease has been found concurring without ApoD over-expression." (PMID 28182653, 2017). "In contrast to cortex, hippocampus, and cerebellum, apolipoprotein D was highly expressed in brainstem tissue from subjects (N = 26, 32−96 years of age) with no history of neurological disease, and expression showed little variation with age." (PMID 24167586, 2013). "The ApoD level was significantly less abundant in RRMS patients, who had clinically isolated syndrome at the time of lumbar puncture, as compared to the patients with other inflammatory and non-inflammatory neurological diseases." (PMID 39767175, 2024).
infection (7 papers, 2021 to 2024). The state of being infected such as from the introduction of a foreign agent such as serum, vaccine, antigenic substance or organism. "Specifically, the infection with r1408-1412 upregulated the expression of a skin mucus lectin, a gene codifying for an apolipoprotein D, apoD, and a VRG, nans." (PMID 34832544, 2021). "It is interesting to note that overexpression of human apoD in neurons of Thy-1/apoD transgenic mice resulted in a threefold increase in the number of mice surviving coronavirus (HCoV-OC43) infection." (PMID 32897518, 2021). "In addition, another two genes that were only deregulated after infection with the double mutant were eomes at 2 days p.i., and, at 3 days p.i., apoD, which reaches one of the highest expression levels (3.94)." (PMID 34832544, 2021). "Of the top 20 contributing proteins for each infection identified by machine learning, 6 were found to be common to both LD and WNV (APOD, C4BPB, C7, HP, ITIH3, PGLYRP2), but with varying degrees of importance in each disease." (PMID 36569838, 2022). "However, ApoD overexpression in cultured cell lines did not influence SARS-CoV-2 replication or infection." (PMID 37343697, 2023). "Finally, Vero E6 cells were transfected with either empty vector (Ctrl) or ApoD prior to infection with increasing concentrations of SARS-CoV-2 (MOI 0.005, 0.01, 0.05 and 0.1), with the extent of infection being determined by N protein immunofluorescence 24 and 48 h post-infection." (PMID 37343697, 2023). "However, overexpression of ApoD in cell-based assays did not alter SARS-CoV-2 replication and infection." (PMID 37343697, 2023). "•ApoD overexpression failed to influence SARS-CoV-2 replication and infection." (PMID 37343697, 2023).
brain disease (2 papers, 2014 to 2020). "Knowledge of endogenous regulatory mechanisms controlling brain disease-triggered ApoD expression is relevant if we want to boost pharmacologically its neuroprotecting potential." (PMID 32559215, 2020).
APOD also shares sentences with these, for which no sentence is quoted: bipolar disorder (6 papers); cardiovascular disease (3); cognitive decline (2); cognitive disorder (2); E. coli infection (2); Parkinson's (2); prion disease (2); renal cell cancer (2); acute coronary syndrome (1); alcohol dependence (1); alcohol use disorders (1); androgen insensitivity syndrome (1); Anxiety (1); arteriosclerosis (1); autism spectrum disorder (1); autoimmune disease (1); bacterial infections (1); benign fibrous histiocytoma (1); brain injury (1); breast tumours (1); central nervous system disorder (1); chronic inflammatory demyelinating polyneuropathy (1); CNS tumors (1); cocaine use disorder (1); cystic disease of the breast (1); dementia (1); dermatofibroma (1); dermatofibrosarcoma protuberans (1); diabetic kidney disease (1); emphysema (1).
A further 30 diseases each share a sentence with APOD in 1 paper.